MCL1 (MCL1 apoptosis regulator, BCL2 family member)
Diseases named in the same sentence as MCL1 in open-access papers (continued):
Sharing a sentence is not in itself a finding about the gene and the disease.
cancer (continued). "The anti-apoptotic proteins BCL-2, BCL-xL and MCL-1 prevent MOMP through directly interacting with the pro-apoptotic proteins, protecting cancer cells from stress stimuli caused by chemotherapies." (PMID 36013602, 2022). "Mcl-1 is an essential Bcl-2 family member that is not only upregulated in several kinds of human cancers but also highly expressed in the myocardium." (PMID 35126811, 2022). "Owing to the dysregulation of myriad pathways that control Mcl-1 expression, cancer cells of diverse lineages tend to overexpress the antiapoptotic Mcl-1 protein." (PMID 36045907, 2022). "Previous reports suggested that induction of MCL-1 in resistant cancer cells is due to either enhanced transcription or protein stability." (PMID 36564381, 2022). "Knockdown of NANOG or HDAC1 with a siRNA robustly dampened expression of the effectors of NANOG signaling, such as CXCL10 and MCL1, across all tested cancer cells." (PMID 35104240, 2022). "For example, the activity of VLCAD has been found to be modulated by myeloid leukemia cell differentiation protein (MCL-1)—a member of B cell lymphoma 2 family antiapoptotic proteins that are overexpressed in cancer cells." (PMID 35178152, 2022). "In fact, MEK1/2 inhibition for the treatment of pediatric solid tumors is under evaluation in clinical trials (NCT02285439, NCT02285439), and several MCL-1 inhibitors for adult cancer treatment." (PMID 35393436, 2022). "One of the possible strategies to overcome the cancer cell resistance towards Bcl-2 or Mcl-1 inhibitors is to use combination of both inhibitors." (PMID 36267274, 2022). "Bcl-xL and Mcl-1 play a key role in survival of cancer cells, and they contribute to protection from apoptosis and promotion of cancer progress." (PMID 35693733, 2022). "Malignant cell clusters shared cancer characteristics and widely significantly overexpressed HLA-A, HLA-B, MCL1, HDAC1, LCK, HSPB1, and IL6R, indicating a common tumor origin." (PMID 36131282, 2022). "MCL-1 is an anti-apoptotic protein that belongs to the Bcl family and is responsible for cancer cell survival and resistance to treatment." (PMID 35834029, 2022). "The overexpression of antiapoptotic proteins, including BCL-2, BCL-XL and MCL-1, contributes to treatment resistance in stem cell-like cancer cells." (PMID 35136016, 2022). "Dysregulation of MCL1 and Bcl2 is noted in cancers and correlates with worse clinical outcomes, thereby rendering them excellent treatment targets." (PMID 35581670, 2022). "Targeting cancer stemness mediated by BMI1/MCL1 with BI‐44 provides the basis for a new therapeutic approach in NSCLC treatment." (PMID 35794816, 2022). "A marked overexpression of Mcl-1 more than any other Bcl-2 family member proteins has been documented in a wide variety of human cancer cell lines." (PMID 36045907, 2022). "The underlying mechanism for the synergistic killing of cancer cells by dinaciclib and TRAIL was associated with the concomitant downregulation of the anti-apoptotic factors cFLIP, MCL-1, and Survivin." (PMID 35884614, 2022). "The natural compound marinopyrrole A has been shown to degrade Mcl-1 protein and thereby induce apoptosis in Mcl-1-dependent cancer cells." (PMID 36045907, 2022). "Other findings showed that Mcl-1 not only influences cancer survival via cytosolic regulation of intrinsic apoptosis but also plays an important role in DNA damage response by facilitating repair of DNA damage directly at the site of damage." (PMID 35887198, 2022). "It has been revealed that in cancer cells, cardiac glycosides induce apoptosis by down-regulating the anti-apoptotic proteins Bcl-XL and Bcl-2 as well as Mcl-1 and increasing the pro-apoptotic proteins Bid and Bax57,58,86–89." (PMID 35778548, 2022). "Clinical studies on Mcl-1 inhibitors are under way, and anticancer effects have been identified in several cancers other than those of the oral cavity." (PMID 35524332, 2022).
cancer (continued). "Previous studies indicated the upregulation of Mcl-1 protein in various cancer cell lines after the use of the inhibitors specific to this anti-apoptotic protein." (PMID 36045272, 2022). "In human cancers, the anti-apoptotic proteins (e.g. Bcl-2, Bcl-XL, and Mcl1) are often upregulated in cancer cells, enabling them to evade apoptotic cell death and losing the capacity to undergo apoptosis in response to chemotherapeutic drugs." (PMID 35532120, 2022). "The multi-kinase inhibitor sorafenib potently induces apoptosis in cancer cells through a mechanism that involves Mcl-1 downregulation." (PMID 36045907, 2022). "Mcl-1 downregulation often proves to be sufficient to induce apoptosis in a variety of cancer cells." (PMID 36045907, 2022). "The MCL-1 protein plays a role in cancer by regulating cell apoptosis through protein–protein interaction (PPI)." (PMID 36557960, 2022). "For example, somatic copy number amplification of both the MCL1 and BCLxL genes in human cancers is an instance of such imbalance." (PMID 35563442, 2022). "Cancer cells escape apoptosis by the upregulating of anti-apoptotic Bcl2 proteins (Bcl2, Bcl-XL and Mcl1), and this upregulation significantly adds to tumor progression, poor prognosis, and chemo resistance." (PMID 36267274, 2022). "Mcl-1 was expressed differentially in all cells, especially in cancer cells, and its expression was downregulated during apoptosis in many cell types in contrast to the anti-apoptotic Bcl-2 and Bcl-XL proteins." (PMID 35632731, 2022). "Our data support a growing body of literature that suggests that the role of each Bcl-2 family protein is determined in a context-dependent manner, leading to differential regulation of Bcl-xL, Mcl-1, and Bcl-2 expression across different cancer types." (PMID 36381235, 2022). "In recent years, many new development of Mcl-1 inhibitors have been designed and entered clinical trial for different types of cancer as mono or combined treatment with Venetoclax." (PMID 36072341, 2022). "Various transcription factors and protein kinases affect Mcl-1 activity, which further facilitates cancer progression." (PMID 35524332, 2022). "It is important to notice that Mcl-1 also was shown to be a prominent regulator increasing sensitivity to mitotic arrest in primary mouse fibroblasts and several carcinoma cell lines sensitive to DiM due to its degradation during mitotic arrest." (PMID 36188556, 2022). "This is the first study to exploit MCL1-mediated vulnerabilities through a DNA repair mechanism versus the BH3-mimetic approaches that aim to sensitize cancer cells to intrinsic apoptosis." (PMID 34475520, 2021). "Especially, downregulation of Mcl-1 by pharmacological inhibitor or gene depletion overcome resistance to TRAIL in many cancer cells." (PMID 35008442, 2021). "For the myeloid cell leukemia sequence 1 (MCL1) transcript for example, alternative splicing of exon 2 generates a protein which either prevents or supports cell death of human cancer cells." (PMID 34445304, 2021). "An overexpression of the anti-apoptotic BCL-XL and MCL-1 protein in PDAC helps cancer cells to avoid apoptosis." (PMID 34575429, 2021). "Overexpression of MCL-1 in cancer cells disrupts the balance between antiapoptotic and proapoptotic proteins, which prevents cancer cells from undergoing apoptosis, resulting in malignant proliferation." (PMID 33883020, 2021). "Mcl-1 became a popular therapeutic target because it is one of the most frequently amplified genes across all human cancers." (PMID 34063867, 2021). "These compounds aim to promote MCL-1-dependent cancer cell apoptosis and exhibit differential activity." (PMID 33883020, 2021). "Increased expression of MCL-1 is a common response to long-term treatment with selective inhibitors of BCL-2/BCL-XL.Therefore, available evidences indicate that MCL-1 is an attractive target for cancer treatment." (PMID 33883020, 2021).
cancer (continued). "Here, using an inhibitory approach, we found that Bak and Bcl-xL regulate sensitivity of cancer cells to Mcl-1 inhibition." (PMID 35008345, 2021). "Further, it has been reported that this natural agent is effective against Mcl-1 overexpressing cancer cells." (PMID 34349655, 2021). "Other miRNAs, such as miR-26a, miR-15a, miR-101 and miR-197, can downregulate the expression of MCL-1 in vivo and inhibit cancer cell growth or apoptosis." (PMID 33883020, 2021). "A number of studies have confirmed the pivotal roles of MCL-1 in cancer cell survival and apoptosis resistance, as in vitro evidence documenting the pro-apoptotic and chemosensitization effects of Mcl-1 knockdown." (PMID 33106913, 2021). "MCL1 (myeloid cell leukemia-1) is a widely recognized pro-survival member of the Bcl-2 (B-cell lymphoma protein 2) family and a promising target for cancer therapy." (PMID 34475520, 2021). "When we applied it to BCP-ALL, we found that trametinib as single agent only produced a modest cytotoxic effect on NALM-6 cells, but when sequentially combined with the MCL-1 inhibitor S63845, it reached an almost complete elimination of these cancer cells." (PMID 34568318, 2021). "Here, we show that genetic deletion of TRIP12 led to FBW7-dependent downregulation of MCL1 protein and enhanced sensitivity to Taxol in cancer cells, phenotypes that were blocked by concomitant FBW7 mutation or deletion." (PMID 33824312, 2021). "Tumor recurrence and drug resistance are associated with high expression of anti-apoptotic proteins, such as MCL-1, that have been increasingly recognized as important targets in cancer therapy." (PMID 34336680, 2021). "Myeloid cell leukemia 1 (MCL1) is an important antiapoptotic member of the BCL2 gene family that is frequently overexpressed in several human cancer types, including CML." (PMID 34564697, 2021). "Cobimetinib combined with venetoclax downgrades the content of the MCL1 protein, and the BCL2:BIM and MCL1:BIM complexes are damaged and release BIM, thus causing apoptosis of cancer cells." (PMID 34976824, 2021). "WP1130 is a DUB inhibitor with some selectivity for USP9X that was shown to reduce MCL-1 and induce cancer cell apoptosis, as well as reduce chemoresistance in various tumor types." (PMID 34203106, 2021). "This pathway, however, is controlled by antiapoptotic Bcl-2 proteins, among them Mcl-1, which is a key regulator of antiapoptotic, prosurvival signaling in cancer cells." (PMID 34028599, 2021). "There is a sufficient evidence to support CDK9 as a valid therapeutic target in cancer through promotion of cell proliferation and regulation of anti-apoptotic proteins such as Mcl-1 and Myc that initiate cancer cell immortality." (PMID 33632038, 2021). "USP9X is a DUB that stabilizes the oncogenic MCL-1 in cancer cells and was shown to be overexpressed in MM." (PMID 34203106, 2021). "MCL1 inhibitors have been developed and are currently investigated in clinical trials in many cancers including MM." (PMID 33445467, 2021). "The upregulation of antiapoptotic BCL-2 family members and MCL-1 functions are two typical approaches exploited by cancer cells to escape apoptosis." (PMID 34336680, 2021). "In addition, undergoing cancer-relevant AS, Mcl-1 could be produced two functionally distinct variants, Mcl-1S (pro-apoptotic) and Mcl-1L (antiapoptotic), in which the latter variant is predominant in cancers." (PMID 34099633, 2021). "MCL1 is essential for the survival of multiple cell lineages and is highly amplified in human cancers." (PMID 34069831, 2021). "Here, we discuss the mechanism by which MCL-1 regulates cancer cell apoptosis and review the progress related to MCL-1 small molecule inhibitors and their role in cancer therapy." (PMID 33883020, 2021). "TRIP12 inactivation causes FBW7 protein accumulation and increased proteasomal degradation of the SCFFBW7 substrate Myeloid Leukemia 1 (MCL1), and sensitizes cancer cells to anti-tubulin chemotherapy." (PMID 33824312, 2021).
cancer (continued). "MCL1 is highly expressed in a variety of human cancer and is often related to chemotherapeutic resistance and relapse." (PMID 33803505, 2021). "Although MCL-1 was the last of the key cancer-associated BCL-2 pro-survival proteins targeted with BH3-mimetics, several potent MCL-1-specific compounds have now been reported." (PMID 34515749, 2021). "MCL1 is a critical FBW7 substrate that is degraded in mitosis by the SCFFBW7 complex, and FBW7 mutations render cancer cells resistant to chemotherapeutic agents targeting the mitotic spindle such as Taxol6,7." (PMID 33824312, 2021). "Small molecule inhibitors with high affinity and specificity to human MCL-1 have been developed and explored for the treatment of certain cancers." (PMID 34336857, 2021). "Since MCL1 emerged as a key mediator of ANO1HIGH cancer cell signaling and survival, we evaluated the potency of a specific MCL1 small-molecule inhibitor currently in clinical trials." (PMID 33803266, 2021). "MCL-1 inhibitors can restart apoptosis when in combination with other therapies, allowing various cancer types to benefit from it." (PMID 33883020, 2021). "MCL-1 is a well-known cancer-related molecule involved in cell proliferation, survival, and metastasis." (PMID 35069696, 2021). "The stability of MCL1 is maintained by SUMOylation at its K234 and K238 sites, which inhibits Tripartite motif-containing 11(TRIM11) -mediate ubiquitination of MCL1 and apoptosis of cancer cells." (PMID 33225418, 2021). "Genetic deletion of TRIP12 stabilised FBW7 and enhanced FBW7-mediated degradation of its substrate MCL1, rendering cancer cells sensitive to the chemotherapy drug Taxol." (PMID 33824312, 2021). "The central role of MCL-1 in regulating the mitochondrial apoptotic pathway makes it an attractive target for cancer therapy." (PMID 33883020, 2021). "Altogether, our results have shown that Bak and Bcl-xL proteins are involved in the sensitivity/resistance of adherent cancer cell lines to Mcl-1 inhibition." (PMID 35008345, 2021). "The Mcl-1 locus was found to be somatically amplified and its expression found to be elevated in multiple human tumor types and cancer cell lines." (PMID 34336857, 2021). "MCL-1 inhibitors in combination with existing radiotherapy/chemotherapy can overcome resistant/relapsed tumors, increasing the disease-free survival of cancer patients." (PMID 33883020, 2021). "The initiation, growth, and progression of cancer lesions have been promoted by Akt-mediated Mcl-1 expression." (PMID 34349823, 2021). "Using the same approach by which MCL-1 was validated as the key survival factor for MCL-1-amplified cancer cells, BCL-XL was knock-down in cell lines in which BCL-XL was amplified, resulted in a pronounced reduction in viability." (PMID 33799592, 2021). "Characterizing these pathways in translational models provides insight into the benefit that cancer derives from the upregulation of MCL1, while also exposing possible combination therapies with emerging MCL1 inhibitors for cancer therapy." (PMID 34475520, 2021). "In this regard, overexpression of anti-apoptotic BCL-2 members (e.g., BCL-2, BCL-XL, MCL-1) is quite frequent in newly diagnosed cancer as well as after developing resistance to therapies." (PMID 33799470, 2021). "Previous observation described that human cancer cells were sensitized to apoptosis induced by Bcl-2/Bcl-xL-targeting BH3 mimetics via hypoxia-mediated downregulation of Mcl-1." (PMID 34257274, 2021). "Mcl-1 is of particular interest as a therapeutic target as it is one of the most frequently amplified genes across all human cancer, including GBM." (PMID 34344865, 2021).
cancer (continued). "Expression of the Stat1 downstream gene Mcl-1 increased in Oct4-overexpressing cancer cells, while Stat1 knockdown in Oct4-overexpressing cancer cells sensitized them to cisplatin-induced apoptosis." (PMID 34685622, 2021). "Previous studies have shown that STAT3 activation subsequently increased c-myc, Bcl-2, and Mcl-1 transcription, thereby inducing cancer cell proliferation and survival." (PMID 33731185, 2021). "Another particularly interesting effect was that of the MPE on Mcl-1—a prominent Bcl-2 family member with an antiapoptotic role, whose overexpression and amplification represent events frequently occurring in human cancers." (PMID 34299603, 2021). "Myeloid cell leukemia-1 (MCL1) is one of the most highly amplified genes in human cancers, with amplifications observed in more than 10% of solid cancer types." (PMID 34638252, 2021). "In recent years, many studies have shown that MCL-1 is essential for the survival and development of cancer cells." (PMID 33883020, 2021). "In many cancers, MCL1 is essential for cancer cells to overcome oncogenic stress-induced apoptosis and for chemotherapeutic resistance and relapse." (PMID 34069831, 2021). "Of these, several are found in genes involved in DNA damage response and double-strand DNA repair mechanisms, including MCL1, ATR, KMT2C, and CBLC, indicating genomic instability and cancer predisposition." (PMID 34299215, 2021). "Given the prominence of MCL-1 inhibitors in cancer therapy, researchers have utilized various approaches to identify a cohort of MCL-1 inhibitors, which are expected to enter clinical trials." (PMID 33883020, 2021). "One further issue with targeting BCL-XL in some cancers, especially solid tumours, is that co-targeting of MCL-1 is required for maximal killing activity." (PMID 34515749, 2021). "Similar to the case of pancreatic ductal adenocarcinoma, anti-apoptotic MCL-1 protein levels are also increased in leukemic cells to maintain cancer survival." (PMID 34575429, 2021). "Mcl-1 is frequently overexpressed in various cancers including ESCC, and it protects tumor cells from apoptosis induced by chemotherapeutic agents, such as cytarabine, daunorubicin, and regorafenib." (PMID 34741018, 2021). "As a negative regulator of apoptosis, Mcl1 has been widely reported as being overexpressed in a number of cancers such as lung and breast, and which can be destabilized by NOXA, through the ubiquitination pathway." (PMID 34753495, 2021). "E3 ubiquitin ligases (Mule, SCFβ-TrCP, SCFFBW7, TRIM17, APC/CCdc20, and FBXO4) and deubiquitinases (USP9X, Ku70, USP13, JOSD1, and DUB3) work together to balance MCL1 stability, which has an important role in the chemoresistance of cancer cells." (PMID 33803505, 2021). "The importance of MCL-1 in cancer was demonstrated in multiple mouse models where Mcl1 deletion has a profound effect on the initiation and development of haematological cancers." (PMID 34515749, 2021). "As it is, amplification of the MCL1 gene locus on chromosome 1q21.2 is highly prevalent in human cancers and correlates with MCL-1 dependency." (PMID 34198580, 2021). "Protein ubiquitination via the regulation of UPS plays a crucial role in anti-apoptotic protein degradation, including Bcl-2, Bcl-xL, and Mcl-1, resulting in the induction of cancer cell death." (PMID 34576269, 2021). "We provide several review articles focusing on MCL-1 as a target for cancer therapeutics for further reading." (PMID 34384473, 2021). "In cancer therapy, MCL1 degradation is an important event for apoptosis in cancer cells that are undergoing mitotic arrest by microtubule-stabilizing agents." (PMID 34475520, 2021). "Strikingly, one of the most common focal amplifications (1q21.2) detected (in 10.9% of all cancers) contains the MCL-1 gene." (PMID 33799592, 2021). "Previous studies have reported that apigenin inhibits the expression of various anti-apoptotic Bcl-2 family proteins, including Bcl-xL, Mcl-1 and Bcl-2 in several cancer cell lines." (PMID 34914725, 2021).